PRDM1 (PR/SET domain 1)
Description:
Transcription factor that mediates a transcriptional program in various innate and adaptive immune tissue-resident lymphocyte T cell types such as tissue-resident memory T (Trm), natural killer (trNK) and natural killer T (NKT) cells and negatively regulates gene expression of proteins that promote the egress of tissue-resident T-cell populations from non-lymphoid organs. Plays a role in the development, retention and long-term establishment of adaptive and innate tissue-resident lymphocyte T cell types in non-lymphoid organs, such as the skin and gut, but also in other nonbarrier tissues like liver and kidney, and therefore may provide immediate immunological protection against reactivating infections or viral reinfection (By similarity). Binds specifically to the PRDI element in the promoter of the beta-interferon gene. Drives the maturation of B-lymphocytes into Ig secreting cells. Associates with the transcriptional repressor ZNF683 to chromatin at gene promoter regions (By similarity). Binds to the promoter and acts as a transcriptional repressor of IRF8, thereby promotes transcription of osteoclast differentiation factors such as NFATC1 and EEIG1 (By similarity).
Synonyms: PRDI-BF1; BLIMP1; Blimp-1
Tractability: PROTAC: UniProt records ubiquitination sites on it; ubiquitination databases record sites on it.
Target class: Enzyme; Transferase
Gene: Protein-coding gene on chromosome 6 (105,993,463 to 106,109,939, forward strand). Ensembl gene ENSG00000057657.
Subcellular location: Nucleus; Cytoplasm
Subcellular location (Human Protein Atlas): Nucleoli; Nucleoplasm
Pathways (Reactome):
Reproduction: Specification of primordial germ cells
Signal Transduction: STAT3 nuclear events downstream of ALK signaling
Gene Ontology:
Molecular function: DNA-binding transcription repressor activity, RNA polymerase II-specific; protein binding; RNA polymerase II cis-regulatory region sequence-specific DNA binding; sequence-specific double-stranded DNA binding; DNA-binding transcription factor activity; promoter-specific chromatin binding; histone methyltransferase binding; transcription cis-regulatory region binding
Biological process: negative regulation of transcription by RNA polymerase II; cell fate commitment; regulation of extrathymic T cell differentiation; regulation of natural killer cell differentiation; regulation of NK T cell differentiation; regulation of transcription by RNA polymerase II; cellular developmental process; gene expression
Cellular component: cytoplasm; nucleolus; nucleoplasm; nucleus
Genetic constraint (gnomAD): Loss-of-function variants: 13 observed, 65.86 expected, observed/expected ratio (o/e) 0.2, 90% interval 0.13 to 0.31. The upper end of that interval is the gene's LOEUF score, 0.31, which puts it in group 1 of 6, group 1 being the genes least tolerant of losing a copy. Missense variants: 895 observed, 1,118.3 expected, observed/expected ratio (o/e) 0.8, 90% interval 0.76 to 0.85. Synonymous variants: 396 observed, 444.35 expected, observed/expected ratio (o/e) 0.89, 90% interval 0.82 to 0.97.
Cancer hallmarks: escaping programmed cell death (suppresses); suppression of growth (promotes); escaping programmed cell death (promotes); invasion and metastasis (promotes); change of cellular energetics; proliferative signalling (promotes); escaping immune response to cancer (suppresses); tumour promoting inflammation (suppresses)
Homologues: Orthologues: chimpanzee PRDM1 (99% identical), macaque PRDM1 (98% identical), pig PRDM1 (89% identical), rabbit PRDM1 (88% identical), mouse Prdm1 (87% identical), guinea pig PRDM1 (87% identical), rat Prdm1 (87% identical), dog PRDM1 (83% identical), tropical clawed frog prdm1 (67% identical), zebrafish prdm1a (54% identical), Drosophila melanogaster Blimp-1 (32% identical), Caenorhabditis elegans blmp-1 (26% identical). Paralogues in human: PATZ1 (13% identical), ZBTB16 (12% identical), PRDM10 (12% identical), ZNF276 (12% identical), PRDM14 (11% identical), HIC1 (11% identical), ZNF362 (11% identical), ZNF76 (11% identical), ZBTB20 (11% identical), ZBTB7C (11% identical), ZNF384 (11% identical), ZNF653 (11% identical), and 24 more.
Diseases named in the same sentence as PRDM1 in open-access papers:
PRDM1 is named in the same sentence as 238 diseases in open-access papers, as found by Europe PMC text mining. Sharing a sentence is not in itself a finding about the gene and the disease. The quoted sentences say what the papers report.
viral infection (39 papers, 2010 to 2025). "PRDM1 encodes a repressor of beta-interferon gene expression and is known to increase during viral infections." (PMID 37175757, 2023). "As a downstream target gene of PHLDA1, it has been that PRDM1 is an important transcriptional repressor that plays multiple roles in viral infection." (PMID 39012348, 2024). "Production of IL10 in CD8+ T cells is directly correlated with level of PRDM1 expression (Blimp-1) during acute viral infection." (PMID 37409113, 2023). "Transcription factor TCF1 is expressed at an extremely high level in Tfh cells post-viral infection and exerts crucial roles in generation, maintenance, and effector functions of Tfh cells by repressing Prdm1 and Il2ra and promoting Bcl6 expression." (PMID 33595435, 2021). "These investigations suggested the complex regulations of PRDM1 in immune response, and our study has provided evidence for PRDM1 to regulate immune response in acute viral infection." (PMID 34956178, 2021). "TCF-1 directly binds to the Bcl6 transcription start site and Prdm1 5′ regulatory regions, which promotes the expression of Bcl6 and represses the expression of Blimp-1 during acute viral infection." (PMID 32766317, 2020). "Deletion of the Prdm1 gene encoding Blimp-1 impaired production of IFN-I, but not other cytokines, upon viral infection or treatment with CpG DNA in pDCs." (PMID 30131810, 2018).
colitis (37 papers, 2012 to 2026). Inflammation of the colon. "NOD mice developed colitis, consistent with previous reports that deletion of Prdm1 in T cells causes spontaneous colitis in mixed 129 and C57BL/6 mice." (PMID 41197380, 2025). "Spontaneous colitis has been reported in mice with T cell-specific deletion of the combination of both Prdm1 and Maf, and this pathology was associated with a unique cluster of Treg cells and the abrogation of Il10 expression." (PMID 38609547, 2024). "To investigate whether Blimp-1 affects SCFA regulation of the pathogenic capacity of Th1 cells in induction of colitis, we generated WT and Prdm1−/− Th1 cells from CD4cre Prdm1fl/fl mice." (PMID 30177845, 2018). "T cell–selective PRDM1 deletion in mice caused early-onset colitis because of excessive CD4+ T cell proliferation, suggesting a major contribution for BLIMP-1 on Treg homeostasis and function." (PMID 40773294, 2025). "To complement these data, we assessed the in vivo functional relevance of Prdm1 deletion in Treg cells using a T cell–adoptive transfer colitis mouse model." (PMID 40680114, 2025). "cMaf and Prdm1 have previously been shown to form part of a coinhibitory receptor–rich Tr1 cell transcriptional signature in mice with experimental colitis." (PMID 36594463, 2023). "In previous studies, we observed an increase in IL-1β production from colonic DCs in acute colitis-induced Prdm1-CKO mice." (PMID 35674135, 2022). "Rag−/− mice which received control Prdm1−/− Th1 cells or butyrate-treated Prdm1−/− Th1 cells developed colitis at similar levels, but more severe than the Rag−/− mice reconstituted with butyrate-treated WT Th1 cells." (PMID 30177845, 2018). "Furthermore, the enhanced IL-2 signaling in the transferred Prdm1-knockout Treg cells likely contributed to the T cell–induced colitis by expanding the number or function of these poorly suppressive “effector” Treg cells." (PMID 40680114, 2025). "Moreover, adoptive transfer of Prdm1-deficient Treg cells into Rag2−/− mice failed to suppress the T cell–induced colitis, likely due to their defective IL-10 production." (PMID 40680114, 2025). "Here, we show that overexpressing Prdm1 down-regulated IL-2 signaling, whereas Prdm1-deficiency enhanced IL-2 signaling in mouse CD4+ T cells and Treg cells with augmented IL-2 signaling in T cells from influenza-infected mice and during adoptive T cell transfer–induced colitis." (PMID 40680114, 2025). "The involvement of PRDM1 in NLRP12 expression have been investigated in skin sensitization and colitis, in which the expression of NLRP12 was also negatively associated with PRDM1 expression." (PMID 34956178, 2021). "Colitis was induced in Rag2−/− mice by intravenously injecting CD45.1+ naïve CD4+ T cells with or without cotransferring CD45.2+ Treg cells from WT or Prdm1-CKO mice." (PMID 40680114, 2025). "Mice lacking Il10 in Treg exhibit mild colitis, but no autoimmunity, while mice with deletion of Prdm1 in Treg show signs of autoimmunity only in aged mice." (PMID 38655862, 2024). "We report here that mice with T cell-specific deletion of Prdm1, Maf or both transcription factors do not develop colitis at the steady state." (PMID 38609547, 2024). "However, adoptively transferred butyrate-treated Prdm1−/− Th1 cells induced colitis at levels similar to control Prdm1−/− Th1 cells in Rag−/− mice, suggesting that butyrate-treated Th1 cells could be endowed with regulatory properties like Tr1 cells in a Blimp-1-dependent fashion." (PMID 30177845, 2018). "The findings that butyrate-treated Prdm1−/− Th1 cells produced lower levels of IL-10 and were not able to control colitis as effectively as butyrate-treated WT Th1 cells indicate the importance of Blimp-1-mediated SCFA induction of IL-10 production in controlling colitis development." (PMID 30177845, 2018).
lymphoma (36 papers, 2008 to 2026). A malignant (clonal) proliferation of B- lymphocytes or T- lymphocytes which involves the lymph nodes, bone marrow and/or extranodal sites. "Based on the histological category of the cancers, other carcinomas, sarcomas, and blood cancers, including lymphomas and myelomas were also assessed for PRDM1-linked survival of patients." (PMID 33972671, 2021). "PRDM1 has been associated to several immune-related diseases, but also to various types of lymphomas." (PMID 23028907, 2012). "Moreover, a recent study using gene expression profiling revealed that PRDM1/BLIMP-1, a master regulator of plasma-cell differentiation, is inactivated in lymphoma where loss of genetic expression correlates with tumor cell proliferation." (PMID 30894186, 2019). "In particular, it has been noted that some cases or cell lines of lymphoma with high levels of PRDM1 mRNA fail to express PRDM1 protein, which implies that post-transcriptional regulation may account for the loss of the PRDM1 protein." (PMID 24438193, 2014). "PRDM1/Blimp1 is a major regulator of terminal B-cell differentiation and is well known as an oncogene in aggressive lymphomas." (PMID 38482011, 2024). "PRDM1 is a master regulator of lymphoid cell differentiation and a tumor suppressor gene in lymphoma." (PMID 39024554, 2024). "In contrast, PRDM1 has been known as the tumor suppressor in the blood cancers, which was consistent in the present analyses on the survival of patients with lymphomas and myelomas." (PMID 33972671, 2021). "Since then, various evidence has indicated that PRDM1/BLIMP1 acts as a tumor suppressor gene in different types of lymphomas derived from B, T, and NK cells, and has a role in the pathogenesis of these diseases." (PMID 32290321, 2020). "Several have already been linked to cancer; for example SP1 is a prognostic factor for lower survival in gastric cancer, PRDM1 to be a tumor suppressor in lymphomas and YY1 as an initiator of tumorigenesis in several malignancies." (PMID 31337866, 2019). "Previously data demonstrated that PRDM1 played a key role in the pathogenesis of human lymphomas being inactivated by a classic mechanism for tumor suppressor genes in non-GCB-DLBCL." (PMID 25232701, 2014). "First, the level of the PRDM1 expression was reciprocal to miR-223 expression in EN-NK/T-NT cases or cultured NK/T lymphoma cell lines." (PMID 24438193, 2014). "PRDM1-fKO NK cells acquired a more stem-like gene signature that could induce a less differentiated, more stem-like phenotype and may promote lymphoma development." (PMID 41366532, 2026). "Also, BCL6 represses PRDM1, a critical factor of plasma cell differentiation, thereby maintaining B cells in an undifferentiated, proliferative state that contributes to lymphoma progression." (PMID 39815148, 2025). "According to the authors, the inactivation of miR-BHRF1-2 could nullify the down-regulation of PR domain zinc finger protein 1/B lymphocyte-induced maturation protein-1 (PRDM1/Blimp1), a pro-apoptotic agent known to suppress the lymphomas." (PMID 35806271, 2022). "Additionally, PRDM1 has been identified as a tumor suppressor gene and found to be inactivated in several lymphomas, including natural killer cell lymphoma (NKCL), diffuse large B cell lymphoma (DLBCL), and anaplastic large T-cell lymphoma (ALCL)." (PMID 35154079, 2021). "Interestingly, the coding gene of Prdm1 that is associated with various cancer developments exhibited the high expression level only in lymphoma, even though all samples included PRDM1 in A compartment enriched in TAD boundaries." (PMID 30894186, 2019). "In addition, we assessed the correlation between PRDM1 and miR-223 using qRT-PCR and western blot analysis of 3 NK/T lymphoma cell lines: YT, NK92, and NKL." (PMID 24438193, 2014). "It is becoming clear that PRDM1 functions as a tumour suppressor gene in lymphomas." (PMID 24438193, 2014).
lymphoma (continued). "In addition, the effect of miR-223 on PRDM1 expression was assessed in NK/T lymphoma cell lines by transfecting a miR-223 mimic or inhibitor to increase or decrease the effective expression of miR-223." (PMID 24438193, 2014). "In addition, some studies supported a role for interference of PRDM1 functions in the pathogenesis of human lymphomas." (PMID 25232701, 2014). "Taken together, these results demonstrate an opposing expression pattern of PRDM1 protein and miR-223 in primary EN-NK/T-NT tissues or in cultured NK/T lymphoma cells, suggesting that miR-223 might regulate the expression of PRDM1." (PMID 24438193, 2014). "miR-9 targets also the transcription factor PRDM1/Blimp1 in lymphoma and may contribute to the phenotype maintenance and pathogenesis of lymphoma cells by interfering with normal B-cell terminal differentiation." (PMID 23431463, 2013). "In the chromatin of B cells, the inactivation of the PRDM1 sequence at the TAD boundary leads to malignant proliferation of B cells, transforming them into lymphoma cells." (PMID 38586584, 2024). "Thus, the PRDM1 sequence may serve as a drug target for future lymphoma therapy." (PMID 38586584, 2024). "The ectopic introduction of PRDM1 in the NK/T lymphoma cell line NKL can induce cell cycle arrest and apoptosis, and the knockdown of PRDM1 in NK cells promotes growth." (PMID 24438193, 2014). "The ΔEBNA2 + Myc lymphomas also express the GC marker CD10 (MME), while ΔEBNA2 lymphomas have higher expression of CD30 (a B cell activation marker), BLIMP1 (PRDM1, a marker for plasma cell differentiation) and BZLF1 (a lytic EBV protein) in comparison to ΔEBNA2 + Myc lymphomas." (PMID 38620028, 2024). "In DLBCL, the expression of PRDM1 appears to be very weak in lymphoma cells, hence the constitutive expression of BACH2 may contribute to maturation arrest of lymphoma cells, leading to lymphomagenesis." (PMID 35008187, 2021). "They showed that PRDM1 was inactivated by a classic mechanism for tumor suppressor genes in non-GCB-DLBCL, strongly supporting that inhibition of post-GC differentiation of B-cells toward plasma cells may play a role in lymphoma pathogenesis." (PMID 25232701, 2014).
lupus (33 papers, 2013 to 2025). "Deficiency in B-lymphocyte-induced maturation protein (BLIMP)-1 in dendritic cells (DCs) (Prdm1) led to a lupus-like phenotype with increased subsets of T follicular helper (Tfh) cells and plasma cells." (PMID 38791389, 2024). "Reduction of Lck, Lat, Zap70 and Prdm1 expression in T cells and a SNP mutation in Ptpn22 have been associated with rheumatoid arthritis, systemic lupus erythematosus and T1D in humans." (PMID 31235823, 2019). "Furthermore, polymorphisms of Prdm1 have been associated with multiple autoimmune diseases, including systemic lupus erythematosus, rheumatoid arthritis, and IBD31–34." (PMID 30177845, 2018). "The ATG5/PRDM1 region has been linked to susceptibility of several autoimmune diseases, including RA and systemic lupus erythematosus (SLE)." (PMID 34101054, 2021). "In this study, we demonstrated that Tfh cells in lupus-prone Prdm1-CKO mice are not only increased in number but are also different functionally from Tfh cells in CTL mice." (PMID 35674135, 2022). "Mice with conditional KO (CKO) of B lymphocyte-induced maturation protein-1 (BLIMP-1) expression in CD11chi DCs (Prdm1 CKO) spontaneously develop a lupus-like disease." (PMID 35674135, 2022). "We found an increase in the number of Tfh cells in secondary lymphoid organs in lupus-prone Prdm1-CKO mice." (PMID 35674135, 2022). "Together, our findings implicate Prdm1 in the regulation of autoimmunity in TECs and are consistent with the identification of polymorphisms in Prdm1 associated with autoimmune diseases, such as systemic lupus erythematosus (SLE)." (PMID 28701508, 2017). "Therefore, we assessed the regulatory T cells in lupus-prone Prdm1-CKO mice." (PMID 35674135, 2022). "Immunoregulatory functions of PRDM1 in myeloid cells have been reported; mice with a DC-specific knockout of Prdm1 (Prdm1 CKO) spontaneously develop a lupus-like phenotype." (PMID 32765503, 2020).